SNORD115-18 (small nucleolar RNA, C/D box 115-18)
Synonyms: HBII-52-18
Gene: Small nucleolar RNA gene on chromosome 15 (25,203,227 to 25,203,308, forward strand). Ensembl gene ENSG00000200163.
Gene Ontology:
Biological process: RNA processing
Cellular component: nucleolus
Homologues: Orthologues: chimpanzee SNORD115 (100% identical), macaque SNORD115 (94% identical). Paralogues in human: SNORD115-17 (100% identical), SNORD115-19 (100% identical), SNORD115-20 (98% identical), SNORD115-12 (96% identical), SNORD115-9 (96% identical), SNORD115-10 (95% identical), SNORD115-11 (95% identical), SNORD115-13 (95% identical), SNORD115-29 (95% identical), SNORD115-36 (95% identical), SNORD115-40 (95% identical), SNORD115-42 (95% identical), and 37 more.